MIR3198-1 (microRNA 3198-1)
Synonyms: hsa-mir-3198-1; MIR3198; mir-3198-1
Gene: MicroRNA gene on chromosome 22 (17,764,180 to 17,764,259, reverse strand). Ensembl gene ENSG00000264757.
Homologues: Orthologues: chimpanzee MIR3198-1 (100% identical).